POU5F1 (POU class 5 homeobox 1)
Diseases named in the same sentence as POU5F1 in open-access papers (continued):
Sharing a sentence is not in itself a finding about the gene and the disease.
cancer (continued). "It has been reported that the transcription factor complex of POU5F1, SOX2, and KLF4 binds to the Nanog promoter to induce cellular reprogramming and cancer stemness." (PMID 32978904, 2020). "This includes OCT4 protein expression, POU5F1, NANOG and SOX2 gene expression in cell lines or cancer-initiating cells." (PMID 32664372, 2020). "IL-22 activates the STAT3 phosphorylation cascade in cancer cells and induces the expression of stem cell markers (SOX2, NANOG, and POU5F1), resulting in increased cancer stemness and tumorigenic potential." (PMID 32670290, 2020). "Expression of cancer stemness-specific genes NANOG and POU5F1 was inhibited in sFRP4 OE cells, whereas sFRP4 SI cells showed elevation in NANOG and POU5F1 gene expression that was much higher than in the untreated U87 control." (PMID 30591679, 2018). "Results of “ChEA 2016” analysis for 96 ≪stemness genes≫ showing elevated expression in TAMRA+ Krebs-2 carcinoma cells relative to TAMRA− cells, with regard to enrichment with SOX2/OCT4/POU5F1/NANOG/KLF4/c-MYC binding sites." (PMID 30505319, 2018). "We also detected upregulation of genes involved in cancer metastasis and cancer stemness (FOXC2, SNAI2, CXCRs, and IGF1), cell stemness (NANOG, POU5F1, and KLF4), metalloproteinases (MMP7, MMP10, and MMP13), and angiogenic factors (IL-8 and S1PR1)." (PMID 28423353, 2017). "RT-qPCR was used to quantify the expression of TROP2 mRNA as well as that of putative markers for basal/cancer stem cells (CD49f, POU5F1 (Oct4), DCLK1, ALDH1A3) or luminal stem cells (NKX3.1) in residual tumors." (PMID 27283984, 2016). "Using a pair of primers that can amplify all known OCT4 isoforms and POU5F1 pseudogenes (designated as ‘Total OCT4’), we detected the mixed OCT4 transcripts in a variety of human cancer cell lines by RT-PCR." (PMID 25625591, 2015). "Other gene fusions involving transcription factors include NUT (or NUTM1), POU5F1, MAML2, NFIB, PLAG1, TFE3, NOTCH, and PAX8 fusions, imparting spatially and/or stochastically dysregulated expression in multiple different cancer types." (PMID 26684754, 2015). "As we have seen in other cancers and cancer cell lines, knockdown of DCLK1 reduced the expression of stem cell pluripotency factors MYC, NANOG, POU5F1/OCT4, and SOX2 in Caki-2 cells." (PMID 25605241, 2015). "Collectively, these results indicated that the AhRs that are constitutively activated by endogenous ITE produced in differentiated cancer cells, specifically bind to the AHRE1 of the POU5F1 promoter in vivo, thereby suppressing the transcription of Oct4." (PMID 26059097, 2015). "However, a significant negative correlation was detected between the expression of the ST6GALNAC1 and two cancer-related biomarkers genes: MYC and POU5F1." (PMID 41152402, 2025). "In various human cancer types, the transcription of POU5F1P1 and POU5F1P5 RNA may modulate the activity of the POU5F1 gene, thereby potentially contributing to carcinogenesis." (PMID 40034124, 2025). "OCT4 (POU5F1), SOX2, and NANOG were expressed at higher levels in cancer cell lines than in MSCs." (PMID 39621192, 2025). "Previous studies have shown that CD276 upregulation promotes the expression of stem cell markers, such as Prominin 1 (PROM1/CD133), CD44, and POU Class 5 Homeobox 1 (POU5F1/Oct4), potentially facilitating the epithelial–mesenchymal transition (EMT) in certain cancers." (PMID 40136662, 2025). "Conversely, pluripotency transcription factors, including NANOG, POU5F1 (encoding OCT4), and TFCP2L1 (encoding LBP9), that control HERVH activity in human ES cells associated with HERVH-CALB1 expression in other cancer types, but not in LUSC." (PMID 37192000, 2023). "Besides, eight processed OCT4 pseudogenes, produced by the POU5F1 gene, exist in different cancer cell lines." (PMID 35875144, 2022). "Moreover, CEP192 was also discovered to be positively correlated with cancer stem cell markers including CD24, SOX9, CD47, and POU5F1 (OCT4)." (PMID 36238304, 2022).
cancer (continued). "Consistent with the gene expression in this study, and protein levels within a previous study, 3D cultured cells had upregulated protein levels of markers for cancer stemness (CD44) and pluripotency (POU5F1), and downregulated levels of markers for proliferation (CCNA2) and differentiation (ERS1)." (PMID 34869246, 2021). "Pluripotency genes, POU5F1 and NANOG, displayed approximately 2–3 fold increases in their protein expression in HT29 cells grown on colorectal PDS compared to 2D, whereas other cancer stem cell markers, such as CD44 decrease by approximately 90%." (PMID 33356003, 2021). "During cancer progression, stemness of cancer cells is maintained by hypoxia through different mechanisms, including enhancement of EMT and the transcriptional induction of stemness related genes (Oct4, POU5F1, Sox2, Nanog, BMI1, Myc and KLF4)." (PMID 33407613, 2021). "There are not any anti-cancer drugs targeting POU5F1, and directly targeting POU5F1 seems to be difficult in CRC treatment." (PMID 33990627, 2021). "POU5F1 may play a vital role in LIHC through CBX3, CCHCR1, and NFYC to regulate some cancer‐related pathways." (PMID 32978904, 2020). "Immunohistochemistry with POU5F1 antibody on specimens with no-ADT exhibited weak positive staining or no staining in luminal cancer cells, whereas positive cytoplasmic staining was noted in basal cells." (PMID 33339129, 2020). "The GSEA results suggested that POU5F1 might participate in the pathological progression of LIHC and other cancers by promoting cell proliferation." (PMID 32978904, 2020). "Although many studies have been performed, the prognostic significance of POU5F1 in cancers remains controversial, and the functions of POU5F1 in the regulatory network of tumors are not fully recognized." (PMID 32978904, 2020). "Cancer stem cells can be identified and isolated due to their specific markers, such as CD44, CD133 (prominin-1), CD117 (c-Kit), ALDH1 (aldehyde dehydrogenase), and OCT3/4 (POU5F1), the transcription factor of the POU (Pit-Oct-Unc) family." (PMID 31083587, 2019). "The human cancer stem cell marker EpCAM and pluripotency genes Nanog homebox, Oct4 (also known as POU class 5 homeobox 1) and Sox2 do not match HOTAIR’s role as an oncogenic factor." (PMID 31097003, 2019). "YY1 shares many properties with cancer stem cells (CSCs) that drive tumorigenesis, metastasis and drug resistance and are regulated by overexpression of certain transcription factors, including SOX2, OCT4 (POU5F1), BMI1 and NANOG." (PMID 27225481, 2016). "When an expanded panel of human cancer cells was analysed, the correlation between the POU5F1 and AHR mRNA levels was still not obvious." (PMID 26059097, 2015). "The transcription of POU5F1 can be suppressed by the tryptophan metabolite, ITE, via a mechanism involving the aryl hydrocarbon receptor, and the combination with a specific AKT inhibitor decreased the proliferation of embryonal carcinoma cells, adherent cancer cells, and CSC-enriched spheres." (PMID 37176108, 2023). "SATB2 may be a driving force for developing cancer stem‐like phenotypes in damaged hepatocytes where induction of stem cell markers (CD44, CD90, EpCAM, AFP and LGR5) and pluripotency maintaining factors (POU5F1/Oct4, Sox‐2, Nanog and KLF4) was prominent." (PMID 35152538, 2022). "Here we provide compelling evidence using both cancer cells with non-edited POU5F1 gene and cancer cells whose POU5F1 gene locus was inserted with a Tag sequence, endogenous OCT4A proteins preferentially bound to the −1826~−1819 bp region of the FOS promoter/enhancer in somatic cancer cells." (PMID 29789579, 2018). "While direct regulation of POU5F1/OCT4 and HNF1A was not explored in this study, it does support an association between these two transcription factors, not only in gastrointestinal cells, but other cancers as well." (PMID 30074477, 2018).
cancer (continued). "According to the cancer stem cell (CSC) dogma, the reactivation of early embryonic stem cell genes such as POU5F1 in somatic stem cells and/or differentiating progenitor cells may lead to transformation into CSCs, which may result in cancer initiation, promotion, and progression." (PMID 26824036, 2015). "In addition to CT genes, BORIS participates in regulation of some non-CT genes such as BRCA1, Oct-3/4 (POU5F1), MYC, Rb2/p130, SBSN and hTERT (human telomerase reverse transcriptase) which are known to be involved in cancer progression." (PMID 30323717, 2018). "However, whether POU5F1 is expressed and Oct4A protein is present in normal and cancer adult tissues and cells remains highly controversial, mainly because the RT-PCR primers and anti-Oct4 antibodies employed did not distinguish Oct4A from other Oct4 isoforms and its pseudogene products." (PMID 25625591, 2015). "In addition, DENSpm-treated cells exhibited elevated levels of expression of several key stem cell markers including POU5F1, Sox9, CD44, BMI1, and Lin28B, although other transcripts that are found in liver stem and cancer stem cells remained absent (PROM1, CD133)." (PMID 30567412, 2018).
tumor (1,148 papers, 2005 to 2026). "POU5F1, also known as OCT4, is a transcriptional factor that has been linked with tumor proliferation, migration, and therapy resistance." (PMID 37325625, 2023). "Of these genes, MALAT1 and POU5F1 remained significantly associated to tumor location after multi‐testing correction." (PMID 33356003, 2021). "Transcription of Mybl2 and Mycn, markers for neoplastic growth and tumor susceptibility, paralleled Pou5f1 expression and decreased as the cardiac program progressed." (PMID 18184438, 2008). "POU5F1 is overexpressed in tumour cells and may be associated with tumour progression and metastasis." (PMID 36685927, 2022). "OCT4 (also known as POU5f1) is one of the key regulators of self-renewal in embryonic stem cells and its overexpression is potentially associated with tumorigenesis, tumor recurrence, and resistance to therapies." (PMID 31963556, 2020). "The OCT4 protein (encoded by Pou5f1) was undetectable in the prints after 5 weeks of differentiation, which is important for implementing this technology in a clinical setting because pluripotency increases the risk of potential tumor formation." (PMID 28386058, 2017). "POU5F1 is a transcription factor and encodes a key regulator of stem cell pluripotency, and has been noted as one of four genes having stem cell potential and being expressed in embryonic stem cells and tumor cells." (PMID 22125590, 2011). "Oncogenic events result in the appearance of tumor cells characterized by increased expression of the stemness marker Pou5f1." (PMID 39684459, 2024). "On the other hand, class II HDACs, particularly HDAC7, are associated negatively with pluripotency markers’ expression in most tumor types, except for OCT4 (encoded by POU5F1), and NANOG in KIRC, KIRP, LGG, LUAD, LUSC, PRAD, and THCA." (PMID 39063083, 2024). "The TCGA results indicate a rise in the expression of the POU5F1 gene from non-tumor samples to primary tumors and subsequently to metastases, although without statistical significance." (PMID 37409260, 2023). "POU5F1 regulates the characteristics of tumor-initiating cells in terms of survival, self-renewal, resistance to drugs, and EMT." (PMID 37325625, 2023). "After 15 days, the subcutaneous tumors were excised, revealing that POU5F1 knockdown resulted in a decelerated tumor proliferation rate, whereas POU5F1 overexpression promoted tumor proliferation." (PMID 38062041, 2023). "The protein encoded by POU5F1 has an essential role in regulating self-renewal, proliferation, DSB repair, and EMT of tumor cells." (PMID 37636389, 2023). "The overexpression of POU5F1 in GC cells was found to stimulate tumor proliferation, migration, and invasion, both in vitro and in vivo." (PMID 38062041, 2023). "Herein, we aimed to identify POU5F1-positive cells involved in tumor heterogeneity and treatment resistance and explore their mechanism of metastasis using organoids in two-dimensional culture (2DOs)." (PMID 37996567, 2023). "In this study, it was observed that POU5F1 exhibited heightened expression in both GC tumor tissues and cell lines." (PMID 38062041, 2023). "Although further experiments are required to demonstrate the roles of stem cell transcription factors in tumor progression, our results suggest that POU5F1 has unique features, at least in the DU145 cell line." (PMID 36564568, 2022). "The overexpression of POU5F1 was remarkably correlated with tumor size, TNM stage, tumor differentiation, tumor invasion depth, lymph node metastasis, distant metastasis, lymphovascular invasion, vascular invasion, tumor number, and tumor recurrence." (PMID 32978904, 2020). "Some studies have come to different or even totally opposite conclusions regarding the prognostic value of POU5F1 and the role of POU5F1 in tumor development." (PMID 32978904, 2020). "Increased POU5F1 was significantly correlated with tumor occurrence (OR = 65.63, p < .001), advanced stage (OR = 2.06, p = .007), and tumor invasion depth (OR = 2.00, p = .001)." (PMID 32978904, 2020).
tumor (continued). "The interaction between NFYC and KAT2A indicates that POU5F1 participates in tumor development through KAT2A‐mediated histone H3 succinylation." (PMID 32978904, 2020). "The typing and quantity conversion of TIICs in normal tissues and tumor tissues indicated the significant meanings of POU5F1 in regulating the tumor immune microenvironment of LIHC." (PMID 32978904, 2020). "The mechanism by which POU5F1 participates in the regulation of the tumor immune microenvironment still needs further study." (PMID 32978904, 2020). "The correlation between POU5F1 and tumor infiltrating immune cells (TIICs) in LIHC was evaluated by CIBERSORT." (PMID 32978904, 2020). "POU5F1 has been studied for a long period of time as a well‐known CSC marker that participates in tumor invasion, differentiation, and recurrence." (PMID 32978904, 2020). "POU5F1 was confirmed as an independent risk factor for LIHC and correlated with tumor occurrence, stage, and invasion depth." (PMID 32978904, 2020). "Previous studies have demonstrated that Gankyrin prevents POU5F1 degradation in HCC and loss of Gankyrin can reduce the oncogenic potential of tumour cells through interaction with MAGE-A4." (PMID 31744479, 2019). "Since KPNA2 is involved in nucleocytoplasmic transport of proteins, we investigated the effects of miR-139 overexpression and KPNA2 depletion on the nucleus transportation of c-myc and POU5F1, which have been reported to promote tumor growth in nucleus." (PMID 31046781, 2019). "Combinations of germ cell pluripotency factors like Nanog, Oct4/Pou5f1, and Sall4 are often used as tumor markers, and some authors even suggest that there is a special connection between induction of meiosis and oncogenesis." (PMID 31752312, 2019). "Beside the fact that SOX2 and POU5F1 indicate increased stemness of cASCs, involvement of those genes in tumor genesis raises questions about autologus stem cell therapy in elderly individuals." (PMID 28246532, 2017). "This implies that the status of the expression of POU5F1/Oct-4 in tumor tissues has the potential to act as a predictor for SLN metastases." (PMID 26931354, 2016). "We have also found out that specific processes leading to induction of reprogramming to pluripotency (depicted by significant overexpression of NANOG, SOX2, and POU5F1) were triggered 20h after the treatment in the tumour cell population exposed to ROS." (PMID 26671576, 2015). "During the formation and expansion of the U87 tumour spheres, there was a gradual increase in the POU5F1 transcript levels starting from 24 h, a point at which no endogenous ITE from the tumour spheres can be detected." (PMID 26059097, 2015). "ITE (10 μM), when replenished at an 8-h interval, blocked the increase in the POU5F1 transcripts in U87 tumour spheres while had minimal effect on other pluripotency factors in 3 days." (PMID 26059097, 2015). "Our findings that POU5F1 can positively regulate MMP-2 expression to promote tumor cell invasion and migration of LACSLCs have important clinical implications." (PMID 24386189, 2013). "A significant post-therapeutic increase in NOTCH2, LGR5 and POU5F1 expression was found in tumours with different tumour regression grades." (PMID 22970250, 2012). "The Pou5f1 gene exhibited a high fold change (2.75) in the transgenic state, which had decreased in the tumor state (fold change 1.70)." (PMID 21464922, 2011). "Furthermore, the heightened activity of POU class 5 homeobox 1 (POU5F1) in CD8+ TEFF cells suggests its critical role in sustaining long-term anti-tumor immunity by preserving residual stemness to mitigate exhaustion." (PMID 41155287, 2025). "Interestingly, in this tumor type PIWIL2 expression negatively correlated with the stem cell markers POU5F1 and NANOG." (PMID 38303021, 2024). "Compared to epithelial cells, POU5F1 expression was significantly higher in tumor cells." (PMID 38191424, 2024).